HNRNPH1 (heterogeneous nuclear ribonucleoprotein H1)
Diseases named in the same sentence as HNRNPH1 in open-access papers (continued):
Sharing a sentence is not in itself a finding about the gene and the disease.
leukemia (2 papers, 2021 to 2023). A malignant (clonal) hematologic disorder, involving hematopoietic stem cells and characterized by the presence of primitive or atypical myeloid or lymphoid cells in the bone marrow and the blood. "The higher level of HNRNPH1 has also been observed in leukemia cell lines and was particularly prominent in CML cells." (PMID 34295818, 2021). "In this study, we demonstrated that downregulation of HNRNPH1 inhibits the potential tumorigenic both in vitro and in vivo, and can increase imatinib sensitivity, providing a rational drug design to prevent the expression of HNRNPH1 in BCR-ABL positive leukemia." (PMID 34295818, 2021). "Furthermore, mRNA and HNRNPH1 protein levels were found to be upregulated in leukemia cell lines compared with BM-MNCs of healthy donors." (PMID 34295818, 2021). "Furthermore, HNRNPH1 was significantly highly expressed in leukemia and embryonal cancer tissues." (PMID 36593250, 2023).
ovarian carcinoma (2 papers, 2021 to 2024). A malignant neoplasm originating from the surface ovarian epithelium. "By activating the GRP78/p38 pathway, HNRNPH1 enhances the stability of LINC00662 and facilitates ovarian cancer progression." (PMID 38405130, 2024).
rhabdomyosarcoma (2 papers, 2018 to 2020). A rare aggressive malignant mesenchymal neoplasm arising from skeletal muscle. "For example, HNRNPH1, an RNA-binding protein highly expressed in many cancers, was found to alter the splicing of some oncogenes following knockdown, which then inhibits the tumor formation and growth in Rhabdomyosarcoma." (PMID 32793288, 2020). "However, the role of HNRNPH1 in other childhood cancers is not well studied, particularly in the most common childhood soft-tissue sarcoma rhabdomyosarcoma (RMS)." (PMID 29362363, 2018).
autoimmune conditions (1 paper, 2025). "hnRNPH1 also has been implicated in diverse non-cancer pathologies, including muscle disorders, cardiovascular diseases, ocular disorders, autoimmune conditions, and viral hepatitis, and its regulatory mechanisms likely involve complex molecular networks and signaling pathways." (PMID 40507967, 2025).
blast crisis (1 paper, 2021). "In the present study, we demonstrated that HNRNPH1 expression was higher in CML patients compared with healthy donors, and gradually elevated along with disease progression that blast crisis patients have significantly highly expressed HNRNPH1." (PMID 34295818, 2021).
brain tumors (1 paper, 2021). "Many oncogenic RBPs such as hnRNPH1, IGF2BP3, HuR, PTB, and SNRPB have been identified and characterized in the context of brain tumors." (PMID 35011618, 2021).
breast invasive carcinoma (1 paper, 2023). "The negative correlation between HNRNPH1 and MYC was found in multiple epithelial cancers such as breast invasive carcinoma (BRCA), COAD, lung squamous cell carcinoma, and ovarian serous cystadenocarcinoma." (PMID 37399401, 2023).
breast tumor (1 paper, 2014). "Previously identified chromatin-associated lncRNAs (CARs) were predominantly downregulated in breast tumor samples, including CARs located in the protein-coding genes for CALD1, FTX, and HNRNPH1." (PMID 25264628, 2014).
enuresis (1 paper, 2021). An elimination disorder characterized by urinary incontinence, whether involuntary or intentional, which is not due to a medical condition and which occurs at or beyond an age at which continence is expected (usually 5 years). "Enuresis is specific to HNRNPD-related disorder (23.1%, n = 3/13), while hypospadias is mostly specific to HNRNPH1-related syndromic ID (40% of missense variants, n = 2/5)." (PMID 33874999, 2021).
female infertility (1 paper, 2022). Diminished or absent ability of a female to achieve conception. "Notably, we find that hnRNPH1 is also essential for oogenesis, and depletion of hnRNPH1 in embryonic female germ cells leads to female infertility with a similar defect in meiosis and cell-cell junction as shown in hnRNPH1-deficient male germ cells." (PMID 35739118, 2022).
gallbladder cancer (1 paper, 2023). "HNRNPH1 expression was significantly lower in HNSCC tissues than in various other diseases but higher in gallbladder cancer and teratoma." (PMID 36593250, 2023).
gastric cancer (1 paper, 2010). A primary or metastatic malignant neoplasm involving the stomach. "Interestingly, a frameshift mutation in HNRNPH1 has been previously identified in gastric cancer." (PMID 20700505, 2010).
Growth delay (1 paper, 2021). A deficiency or slowing down of growth pre- and postnatally. "A subset of probands have growth delay (30.5%, n = 61/200), particularly probands with variation in HNRNPH1 (62.5%, n = 5/8), HNRNPH2 (47.8%, n = 11/23), HNRNPR (90%, n = 9/10, significantly more so than HNRNPK probands [p = 0.03]), and HNRNPUL2 (50%, n = 3/6)." (PMID 33874999, 2021).
heroin addiction (1 paper, 2015). "Furthermore, the human intronic SNP rs9479757 in OPRM1 was associated with heroin addiction severity and decreased binding affinity of HNRNPH1, resulting in exon 2 skipping." (PMID 26658939, 2015).
HNRNPU-related disorder (1 paper, 2021). "Overall, our phenotypic analyses of the previously reported HNRNPU-related disorder, AKS, Bain-type ID, HNRNPH1-related syndromic ID, and HNRNPR-related syndrome are consistent with what has been published." (PMID 33874999, 2021).
Infertility (1 paper, 2022). "Another interesting finding in the current study is that the female hnRNPH1 cKO mice were also infertile and showed similar meiotic defects as hnRNPH1 cKO male mice." (PMID 35739118, 2022). "To explore the molecular reasons for infertility in hnRNPH1 cKO females, we examined the expression of hnRNPH1 in the ovaries at embryonic day 17.5 (E17.5), when most female germ cells have developed to the pachytene stage." (PMID 35739118, 2022).
intellectual impairment (1 paper, 2023). "Interestingly, HNRNPH1 missense mutations in the nuclear localisation sequence and nonsense mutations leading to reduced protein levels have been identified in individuals with neurodevelopmental disorders and intellectual impairment." (PMID 37248947, 2023).
keratosis (1 paper, 2024). A skin disorder consisting of hypertrophy of the stratum corneum of the skin. "For expanded gene families, we found three genes were associated with skeletal development and/or bone density (HNRNPH1, LIN28A, and TARP) and two genes (FTH1 and KDSR) were related to keratosis." (PMID 39092175, 2024).
lung adenocarcinoma (1 paper, 2025). A carcinoma that arises from the lung and is characterized by the presence of malignant glandular epithelial cells. "This suggests that MACC1 influences the splicing outcomes of specific genes by regulating hnRNPH1 activity, which was observed in a lung adenocarcinoma model." (PMID 40507967, 2025). "In lung adenocarcinoma, hnRNPH1 interacts with the MACC1 protein (via its GYR domain binding to the MACC1 SH3 domain) to prevent the skipping of exon 11 in the IRAK1 gene’s pre-mRNA, thereby promoting the production of the oncogenic IRAK1-L isoform, driving tumorigenesis." (PMID 40507967, 2025).
mantle cell lymphoma (1 paper, 2024). Mantle cell lymphoma is a rare form of malignant non-Hodgkin lymphoma affecting B lymphocytes in the lymph nodes in a region called the ``mantle zone''. "According to a different study, splicing of HNRNPH1 is impacted by silent and non-coding mutations, which also negatively impacts the prognosis of mantle cell lymphoma patients." (PMID 39584923, 2024). "The association of mantle cell lymphoma (MCL) with HNRNPH1 mutations leads to increased expression of both the protein and HNRNPH1 mRNA." (PMID 39584923, 2024).
medulloblastoma (1 paper, 2023). A malignant, invasive embryonal neoplasm arising from the cerebellum. "TCPs may be the cells of origin of group 3 medulloblastoma and can be identified by two signature markers, HNRNPH1 and SOX11." (PMID 37568705, 2023). "Therefore, sampling HNRNPH1 and SOX11 in tumor specimens and correlating their expression with the risk of metastasis may represent a future prognostic strategy in this group of medulloblastoma." (PMID 37568705, 2023).
multiple sclerosis (1 paper, 2025). A progressive autoimmune disorder affecting the central nervous system resulting in demyelination. "In an experimental autoimmune encephalomyelitis model of multiple sclerosis, the deletion of hnRNPH1 significantly inhibited Th17 cell differentiation and migration, attenuating neuroinflammation." (PMID 40507967, 2025). "In multiple sclerosis, aberrant hnRNPH1 expression may affect immune cell function and neuroinflammatory responses by regulating the AS of key genes such as IL7R and SP140." (PMID 40507967, 2025).
muscle disorders (1 paper, 2025). "hnRNPH1 has been implicated in muscle disorders, particularly in the pathogenesis of Myotonic Dystrophy type 1 (DM1), a multisystemic disorder affecting skeletal muscle and characterized by aberrant RNA splicing." (PMID 40507967, 2025). "In other systems, hnRNPH1 influences muscle disorders, cardiovascular function, ocular development, and other pathologies, though the specific mechanisms governing these roles require further elucidation." (PMID 40507967, 2025).
myeloma (1 paper, 2025). "According to the research results of cell type-specific regulatory activity, the most activated TFs in these myeloma cell subgroups included ETV7(C0 GNB2L1+ NK cells), TAF1(C1 RACK1+ NK cells), POU2F2(C2 HNRNPH1+ NK cells), and RUNX2(C3 ATP5E+ NK cells)." (PMID 40454289, 2025).
neuroblastoma (1 paper, 2025). Neuroblastoma (NB) is the most common solid, extracranial childhood tumor. "We next assessed the association of HNRNPH1 abundance with TCF3 transcript variant ratios in neuroblastoma in further detail." (PMID 40766465, 2025). "Extending this finding, we present evidence that in neuroblastoma, HNRNPH1 is a MYCN target, potentially explaining the higher levels of HNRNPH1 and TCF3-exon 18a transcript variants in this tumor type." (PMID 40766465, 2025). "In our study, we observed that neuroblastomas exhibit one of the greatest imbalances in the expression of TCF3 transcripts variants, with TCF3-exon 18a transcripts dominating and that this tumor type also expresses slightly higher levels of HNRNPH1 than other solid tumor types." (PMID 40766465, 2025).
pulmonary arterial hypertension (1 paper, 2025). Pulmonary arterial hypertension (PAH) is a group of diseases characterized by mean pulmonary artery pressure >20 mmHg and elevated pulmonary arterial resistance leading to right heart failure. "The role of hnRNPH1 is particularly notable in pulmonary arterial hypertension (PAH)." (PMID 40507967, 2025).
rheumatoid arthritis (1 paper, 2025). A chronic, systemic autoimmune disorder characterized by inflammation in the synovial membranes and articular surfaces. "hnRNPH1 functions as an autoantigen in conditions such as systemic lupus erythematosus and rheumatoid arthritis (RA), and the presence of autoantibodies against hnRNPH1 may correlate with disease onset and progression." (PMID 40507967, 2025).
sterility (1 paper, 2022). "After 5 months of fertility testing, all hnRNPH1 cKO female mice were also showing complete sterility." (PMID 35739118, 2022).
Strabismus (1 paper, 2021). A misalignment of the eyes so that the visual axes deviate from bifoveal fixation. "Of eye abnormalities (41.2%, n = 82/199), strabismus is the most common, observed frequently in HNRNPAB-related disorder (66.7%, n = 2/3), HNRNPH1-related syndromic ID (62.5%, n = 5/8), and HNRNPR-related syndrome (55.6%, n = 5/9)." (PMID 33874999, 2021).
tumor (31 papers, 2007 to 2026). "In our xenograft studies, we found that HNRNPH1 KD caused a profound defect in tumor formation and growth." (PMID 29362363, 2018). "Interestingly, the list of the top 100 significant differentially methylated genes contained tumor-associated genes HNRNPH1 (top two), HOXA9 (top seven) and HIST1H2BM (top thirty-seven) among the top matched." (PMID 36358793, 2022). "Overall, positive expression of HNRNPH1 is associated with poor tumour differentiation degree." (PMID 30857150, 2019). "Together, these data reveal an association between the levels of HNRNPH1 expression and tumor growth in vitro and in vivo, suggesting that downregulating HNRNPH1 may inhibit RMS growth." (PMID 29362363, 2018). "Silencing HNRNPH1 in vivo inhibits the tumor growth of patient-derived GBM cell-originated intracranial xenografts and has significant survival benefits." (PMID 41872153, 2026). "Together, our results show the critical importance of HNRNPH1 in cell cycle progression and tumor growth, potentially impacting the development of novel strategies to treat GBM." (PMID 41872153, 2026). "Despite the disparity in sample sizes within the HPA database, which includes 10 normal samples and 100 tumor samples, we identified HNRNPH1, FUS, and HNRNPU as proteins that are highly expressed in GBM." (PMID 40340965, 2025). "In rhabdomyosarcoma, hnRNPH1 suppresses tumor growth by regulating the AS of genes such as CTNNB1 and MDM4, leading to G1-phase cell cycle arrest." (PMID 40507967, 2025). "From these RBPs, only HNRNPH1 is differentially expressed between tumor core and peripheral neoplastic cells, while four RBPs (HNRNPH1, HNRNPF, TRA2A, DDX42) are reported to be differentially spliced themselves." (PMID 39936571, 2025). "Regarding drug sensitivity, aberrant hnRNPH1 expression or activity is closely correlated with tumor cell responses to therapeutics." (PMID 40507967, 2025). "In ovarian cancer, hnRNPH1 promotes tumor cell proliferation, migration, and invasion by stabilizing the long non-coding RNA (lncRNA) LINC00662, which indirectly leads to GRP78 upregulation and activation of the p38 MAPK signaling pathway." (PMID 40507967, 2025). "Additional analyses showed that HRAS exon 5 PSI is positively correlated with HNRNPH1 gene expression across tumor types and negatively correlated with HNRNPF expression." (PMID 37399401, 2023). "Together, these data suggest a permanent downregulation of caspase-7 in CRC by the TRIM25-dependent activation of hnRNPH1, which functionally contributes to the apoptosis resistance of tumor cells." (PMID 36611995, 2023). "Our 2D-PAGE revealed some fragments to be upregulated while 1D-WB showed upregulation of HNRNPF and perturbation of HNRNPH1/2 in the central as well as in the peripheral part of the tumor." (PMID 34563043, 2021). "Previous studies have confirmed that the high expression of HNRNPH1 can promote tumor development by inhibiting tumor suppressor genes." (PMID 35003307, 2021). "We then recapitulated this finding by performing in vivo xenograft studies, in which knockdown of HNRNPH1 resulted in a reduction of tumor formation and growth." (PMID 29362363, 2018). "With these findings, we add to the growing knowledge that HNRNPH1 plays a prominent role in tumor survival, including that of RMS." (PMID 29362363, 2018). "This is highly suggestive that HNRNPH1 KD results in cellular death, but cells with low shHNRNPH1 expression (and thus higher HNRNPH1 expression) are able to repopulate the tumor after a prolonged period of time." (PMID 29362363, 2018). "We showed that at an early time-point (day 17, which is 5 days after doxycycline treatment), reduced tumor growth corresponds to knockdown of HNRNPH1." (PMID 29362363, 2018). "In summary, we show that HNRNPH1 is vital for tumor survival, most likely through regulation of cell proliferation and cell death." (PMID 29362363, 2018).
tumor (continued). "In Group 1, inducing HNRNPH1 KD immediately after cell transplantation dramatically inhibited tumor growth of both RD and RH30 cells, consistent with the growth inhibition observed in vitro." (PMID 29362363, 2018). "Nevertheless, HNRNPH1 KD either immediately at tumor implantation or after tumor development significantly reduced tumor growth, suggesting that HNRNPH1 is a valid antitumor therapeutic target for the treatment of RMS." (PMID 29362363, 2018). "In cancer, hnRNPH1 often acts as a pro-tumorigenic factor, albeit in a context-dependent manner, influencing the alternative splicing of crucial oncogenes, mRNA stability, and tumor cell sensitivity to therapeutic agents." (PMID 40507967, 2025). "hnRNPH1 knockdown also significantly inhibited tumor growth in a nude mouse xenograft model." (PMID 40507967, 2025). "Seven potential tumor antigens, [SREBF1, LUC7L3, LAMA5, PCGF3, HNRNPH1, KLC4, and OFD1], which were associated with nonsense-mediated mRNA decay factor expression, overall survival, and infiltration of APCs and would thus induce a potent anti-tumor T-cell response." (PMID 39399167, 2024). "HNRNPH1 regulates AS of target genes to promote tumor progression." (PMID 38405130, 2024). "Moreover, lncRNAs are involved in tumor-associated immune regulation, and the IFN-associated lncRNA INCR1 binds hnRNPH1, thereby preventing it from negatively affecting the expression of neighboring genes PD-L1 and JAK2." (PMID 36118202, 2022). "Given that the reduction of PARG activity can significant elevate the PARylation cellular level, implying that PARG inhibitors may block the HNRNPH1 related tumor growth." (PMID 34295818, 2021). "The oncogenic properties of heterogeneous nuclear ribonucleoprotein H1 (hnRNP H1) have been reported, although the tumor-promoting mechanism remains unclear." (PMID 32630435, 2020). "Additionally, in established and actively growing tumors, HNRNPH1 KD initially halted tumor growth; however, the tumors eventually regained their growth kinetics." (PMID 29362363, 2018). "This also supports the hypothesis that HNRNPH1 depletion diminishes tumor growth by activating apoptosis pathways." (PMID 29362363, 2018). "To determine whether HNRNPH1 KD reduces the tumor burden of mice with existing tumors, we treated a cohort of mice with doxycycline after their tumors were palpable (Group 2)." (PMID 29362363, 2018). "To determine whether HNRNPH1 KD also inhibits RMS tumor growth in vivo, we generated doxycycline-inducible HNRNPH1 shRNA stable RD and RH30 cells." (PMID 29362363, 2018). "The HNRNPH1 reduction could inhibit the tumor size compared with the control in vivo." (PMID 34295818, 2021). "To confirm that HNRNPH1 KD reduces the tumor burden we treated a second cohort of mice with doxycycline after their tumors were palpable and examined the relationship between tumor volumes and protein levels of HNRNPH1 at earlier time points after doxycycline treatment." (PMID 29362363, 2018). "In non-small cell lung cancer, hnRNPH1, regulated by MYC, mediates a splicing switch of KHK pre-mRNA from the KHK-C to the KHK-A isoform, promoting metabolic reprogramming to support tumor growth." (PMID 40507967, 2025). "Further analysis of the shared 61 proteins revealed that there were a large number of tumor-related proteins, such as HSPA5, HNRNPH1, HSPA8, TGM3, and SERPINB12." (PMID 37715221, 2023). "In this study, HNRNPH1 and WDR81 were highly expressed in OTSCC tumor samples and were protective genes for predicting prognosis." (PMID 36593250, 2023). "In our study, we identified a series of potential tumor antigens, including SREBF1, LUC7L3, LAMA5, PCGF3, HNRNPH1, KLC4, and OFD1, by systematically analyzing alternative splicing and mutation of genes in patients with HNSCC." (PMID 36467412, 2022). "Our in vitro and in vivo findings indicate that genetic downregulation of HNRNPH1 leads to inhibition of RMS cell and tumor growth." (PMID 29362363, 2018).